Y_RNA (Y RNA )
Gene: Miscellaneous RNA gene on chromosome 11 (93,719,603 to 93,719,715, forward strand). Ensembl gene ENSG00000199875.
Homologues: Orthologues: chimpanzee Y_RNA (99% identical), macaque Y_RNA (92% identical). Paralogues in human: RNY1 (88% identical), Y_RNA (87% identical), Y_RNA (86% identical), Y_RNA (85% identical), Y_RNA (84% identical), RNY1P8 (83% identical), Y_RNA (83% identical), RNY1P11 (82% identical), Y_RNA (82% identical), RNY1P10 (81% identical), Y_RNA (81% identical), RNY1P5 (81% identical), and 94 more.